RORA (RAR related orphan receptor A)
Diseases named in the same sentence as RORA in open-access papers (continued):
Sharing a sentence is not in itself a finding about the gene and the disease.
gastric cancer (20 papers, 2012 to 2025). A primary or metastatic malignant neoplasm involving the stomach. "We analyzed the correlation between RORA expression and immune checkpoint-related genes, as well as tumor mutation burden in gastric cancer." (PMID 40638694, 2025). "Low expression levels of RORα were associated with poor overall survival in gastric cancer patients." (PMID 41425709, 2025). "RORα was down-regulated in human gastric cancer tissues, and this reduction was associated with the progression and poor prognosis." (PMID 28052040, 2017). "Our study here for the first time demonstrated that RORα was significantly reduced in human gastric cancer tissues, which is associated with the clinical stages and lymph node metastasis." (PMID 28052040, 2017). "The results indicate that RORα level is associated with the progression and prognosis of gastric cancer." (PMID 28052040, 2017). "To further determine the association of RORα with gastric cancer, we employed human gastric cancer cell lines." (PMID 28052040, 2017). "The mechanisms underlying RORα reduction in human gastric cancer were due to the decreased AMPK, leading to less apoptosis." (PMID 28052040, 2017). "In summary, RORα is down-regulated in human gastric cancer, which causes the resistance to apoptosis in gastric cancer cells." (PMID 28052040, 2017). "However, the mechanisms underlying RORA’s role in EBV-associated gastric cancer (EBVaGC) remain to be elucidated." (PMID 40638694, 2025). "However, the association of glycolysis with RORα in regulating gastric cancer (GC) proliferation remains poorly understood." (PMID 38184549, 2024). "Our study reveals the molecular characteristics of EBV-associated gastric cancer, establishes a prognostic model for RORA in gastric cancer, and demonstrates that EBV-miR-BART5-5p may target and inhibit RORA to promote gastric cancer cell proliferation and migration." (PMID 40638694, 2025). "Therefore, we hypothesize that RORα is dysfunctional in gastric carcinoma and this causes decreased apoptosis in gastric cancer cells." (PMID 28052040, 2017). "The RORα agonist can increase the apoptosis of GC SGC7901 cells, while its reverse agonist SR3335 can reduce the 5-FU-mediated apoptosis, suggesting that RORα promotes the apoptosis of human gastric cancer cells." (PMID 41425709, 2025). "In gastric cancer, RORA expression was significantly reduced in tumor tissues compared to normal tissues." (PMID 40638694, 2025). "We then analyzed the TCGA dataset to investigate the differential expression and prognostic significance of RORA in gastric cancer." (PMID 40638694, 2025). "The results indicated that RORA expression was significantly upregulated in CD8 + T cells within gastric cancer." (PMID 40638694, 2025). "Due to significant differences between cell subtypes, we selected the gastric cancer single-cell dataset (GSE134520) from the TISCH database to investigate the distribution of RORA across different cell subtypes." (PMID 40638694, 2025). "Our previous proteomic analysis showed that DADS can significantly upregulate the expression of RORα in human gastric cancer MGC803 cells." (PMID 41425709, 2025). "Analysis of the TCGA database was performed to evaluate RORA expression and its prognostic significance in gastric cancer, as well as its correlation with immune response, tumor mutational burden, and drug sensitivity." (PMID 40638694, 2025). "Further investigation is needed to elucidate the specific mechanisms of RORA in gastric cancer and to assess its potential as a therapeutic target in clinical settings." (PMID 40638694, 2025). "Further analysis demonstrated that RORA expression in gastric cancer is positively correlated with immune checkpoint-related genes, including NRP1 and CD40." (PMID 40638694, 2025). "We then investigated miR-BART5-5p in EBV-positive gastric cancer and identified RORA as a potential target gene." (PMID 40638694, 2025).
gastric cancer (continued). "In summary, our study demonstrates that RORα inhibits gastric cancer proliferation by attenuating the glycolytic ability induced by G6PD and PFKFB3 in GC." (PMID 38184549, 2024). "In summary, these results indicate that RORα plays a crucial role in gastric cancer proliferation and glycolysis by modulating G6PD and PFKFB3 genes." (PMID 38184549, 2024). "CircGSK3B directly binds to EZH2 and inhibits the binding of EZH2 and H3K27me3 to the RORA promoter, leading to elevated RORA expression and inhibiting tumor progression by suppressing the growth, invasion, and metastasis of gastric cancer cells." (PMID 35116058, 2021). "Utilization of RORα agonist or AMPK activator would be a potential therapeutic strategy for the treatment of gastric cancer." (PMID 28052040, 2017). "Further study is required to determine the role of RORα in regulating proliferation, migration, invasion of gastric cancer cells, and chemotherapy sensitivity, as well as in animal model of gastric cancer." (PMID 28052040, 2017). "We found that RORα activation induced apoptosis, whereas its knockdown by siRNA or pharmacological inhibition reduced apoptosis in gastric cancer cells." (PMID 28052040, 2017). "The protein levels of RORα determined by Western blot were significantly reduced in human gastric cancer cells SGC-7901 and AGS cells as compared to normal gastric epithelial cells GES-1." (PMID 28052040, 2017). "The levels of AMPKα are decreased in the early stage of gastric cancer, and patients with gastric carcinoma often have a favorable prognosis with positive expression of AMPK, suggesting the reduced RORα phosphorylation/activation in gastric cancer." (PMID 28052040, 2017). "Altogether, these results suggest that the RORα reduction in gastric cancer is possible due to the decrease in AMPK, which leads to its recruitment on tumor suppressor genes." (PMID 28052040, 2017). "We employed both genetic and pharmacological approaches to determine the role of RORα in regulating apoptosis in gastric cancer cells." (PMID 28052040, 2017). "Taken together, RORα reduction occurs in gastric cancer leading to the survival of tumor cells, which is attenuated by AMPK." (PMID 28052040, 2017). "AMPK has been shown to increase the expression of tumor suppressor genes including F-box and WD repeat domain containing 7 (FBXW7), semaphorin III/F (SEMA3F), and p21Cip1 (p21) in gastric cancer cells, and RORα functions a transcription activator." (PMID 28052040, 2017). "To understand the relationship of RORα and ILC2s-related markers and signature cytokines in patients with gastric cancer, we analyzed the correlation between RORα and T1/ST2, IL-17RB, CRTH2, ICOS, CD45, IL-13, and IL-5 in mRNA levels." (PMID 24741632, 2014). "RORα has also been identified as one of the methylation-silenced genes in gastric cancer cell lines, which favors the concept that reduced RORα expression promotes cancer progression." (PMID 23443091, 2012). "Similarly, research in the field of cancer provides support for our findings, with studies on glioblastoma, gastric cancer, and endometrial cancer also identifying an inhibitory effect of Rorα on cell migration." (PMID 40563503, 2025). "This suggests that EBV-miR-BART5-5p may promote gastric cancer cell proliferation and migration by regulating RORA." (PMID 40638694, 2025). "Moreover, RORα expression inversely correlates with G6PD and PFKFB3, and low RORα combined with high G6PD or PFKFB3 predicts poor survival in gastric cancer, indicating RORα as a potential biomarker and therapeutic target." (PMID 41425709, 2025). "Finally, we elucidated that miR-BART5-5p likely promotes gastric cancer cell proliferation and migration through the regulation of RORA." (PMID 40638694, 2025). "Tumor mutation burden analysis revealed a significant negative correlation between RORA expression and tumor mutation burden in gastric cancer." (PMID 40638694, 2025).
gastric cancer (continued). "In summary, our database analysis and experimental results provide strong evidence that EBV-miR-BART5-5p may promote gastric cancer cell proliferation and migration by targeting and inhibiting RORA." (PMID 40638694, 2025). "In this study, we explored the biological function of miR-BART5-5p in EBVaGC and discovered that miR-BART5-5p might promote gastric cancer cell proliferation and migration by regulating RORA." (PMID 40638694, 2025). "We also employed the gastric cancer cell lines to determine the mechanisms for RORα dysregulation and whether RORα promotes apoptosis." (PMID 28052040, 2017). "We hypothesize that RORα is dysregulated in gastric cancer and this dysregulation reduces the apoptosis in gastric cancer cells." (PMID 28052040, 2017). "This may serve a mechanism for progression of gastric cancer through reduced apoptosis in cancer cells when RORα is significantly ameliorated." (PMID 28052040, 2017). "Furthermore, we measured RORα mRNA level in gastric cancer tissues and matched adjacent gastric mucosa." (PMID 28052040, 2017). "The mechanisms underlying RORα reduction is due to the reduced activation of AMP-activated protein kinase (AMPK), as a selective AMPK activator AICAR increased RORα activation and level in human gastric cancer cells." (PMID 28052040, 2017). "It remains unknown whether RORα reduces glycolysis in gastric cancer thereby reducing their proliferation." (PMID 28052040, 2017). "To test this hypothesis, we employed human gastric cancer tissues with different stages to determine RORα expression, as well as in vitro human gastric cancer cells to determine how RORα is reduced during apoptosis." (PMID 28052040, 2017). "Although RORα suppresses breast tumor invasion, it is unknown whether RORα is dysregulated in gastric cancer leading to cellular survival." (PMID 28052040, 2017). "In addition to phosphorylation, RORα mRNA was also augmented in gastric cancer cells treated with AICAR, although AMPK siRNA or overexpression approaches would further support these data." (PMID 28052040, 2017). "In the present study, we have shown the novel role of RORα in human gastric cancer." (PMID 28052040, 2017). "However, whether DADS inhibits invasion and EMT, and drug resistance in human gastric cancer cells through PKCα-dependent phosphorylation mediated reduction of RORα/β-catenin signaling remains to be further investigated." (PMID 41425709, 2025). "However, there are no reports regarding the regulation of RORα in gastric cancer and whether RORα modulates apoptosis in gastric cancer cells." (PMID 28052040, 2017). "Similarly, the reduction of RORα abundance in gastric cancer tissues was confirmed by Western blot." (PMID 28052040, 2017). "Experimental data further demonstrated that RORA is expressed at lower levels in EBV-positive gastric cancer cell lines and that EBV-miR-BART5-5p targets the 3’ UTR of RORA." (PMID 40638694, 2025). "This study, through pan-cancer analysis and TCGA-STAD dataset analysis, revealed that RORA expression levels in gastric cancer (GC) tissues are significantly lower than in normal tissues, a finding further validated by immunohistochemical staining in the Human Protein Atlas (HPA) database." (PMID 40638694, 2025). "The results revealed significantly higher RORA expression in AGS and MKN-45 compared to SNU719, indicating a notable difference in RORA expression between EBV-negative and EBV-positive gastric cancer cell lines." (PMID 40638694, 2025). "The study found that six genes (MINT25, RORA, GDNF, ADAM23, PRDM5, MLF1) presented differential methylation between gastric cancer and normal mucosa in the training and test population." (PMID 32489454, 2020). "The mRNA expression levels of RORα and GATA3 were significantly increased in patients with gastric cancer compared with healthy controls." (PMID 24741632, 2014).
gastric cancer (continued). "In addition, we found that the cytotoxic mechanism of RORα/γ agonists is mediated through c-myc inhibition not only in CRC cells but also in lung cancer cells and gastric cancer cells." (PMID 36316442, 2022). "Positive expression of RORα in gastric carcinoma was significantly lower than matched noncancer mucosa and paracancerous tissue." (PMID 33336001, 2020). "Furthermore, AICAR treatment increased RORα recruitment on the promoters of tumor suppressor genes (i.e., FBXM7, SEMA3F and p21) leading to apoptosis in human gastric cancer cells." (PMID 28052040, 2017). "Therefore, both RORα and AMPK are potential targets for the intervention and therapy in gastric carcinoma." (PMID 28052040, 2017). "Overall, these finding suggest that AMPK regulates RORα through both transcription and posttranslational modifications, and that RORα may be a potential novel therapeutic target for AMPK-induced apoptosis in gastric cancer cells." (PMID 28052040, 2017). "RORα has been shown to activate AMPK in liver tissues, which raises the question whether there have a positive feedback between AMPK and RORα in regulating the progression of human gastric cancer." (PMID 28052040, 2017). "Our data showed that the mRNA expression levels of the transcription factors RORα and GATA3, the receptors T1/ST2 and IL-17RB, surface markers CRTH2, and type 2 cytokines IL-33, IL-5, and IL-4 were significantly increased in PBMCs from patients with gastric cancer compared to healthy controls." (PMID 24741632, 2014). "Among these 6 regulators RAR-related orphan receptor A (RORA) was down-expressed in 8 types of cancers (Except that Glioblastoma with over-expression and no significant expression in prostate and gastric cancers)." (PMID 24796549, 2014).
melanoma (20 papers, 2014 to 2025). A malignant, usually aggressive tumor composed of atypical, neoplastic melanocytes. "Consistent with findings from the Benna study, this reduction and the presence of rs339972 C and rs10519097 T alleles of RORA were linked to a decreased risk of developing melanoma." (PMID 40191195, 2025). "Nevertheless, we identified an interesting relationship between melanoma susceptibility and RORA polymorphisms acting in sex-specific manner and which is worth further future investigation." (PMID 33549124, 2021). "In particular, the analyzed RORA polymorphisms have different effect on melanoma susceptibility whereas rs339972 minor allele has a protective effect on premenopausal women while rs10519097 minor allele has a protective effect exclusively in men." (PMID 33549124, 2021). "Our results indicated that two SNPs of the RORA clock gene are associated with melanoma susceptibility." (PMID 33549124, 2021). "Recently, two variants in the RORA locus were found to be associated with melanoma prognosis, rs782917 and rs17204952 as well as rs7253062 in DNMT1, a steroid hormone receptor as well." (PMID 33549124, 2021). "It was also shown that RORα and RORγ are expressed in normal and pathological human skin, and that decreased expression of RORα and RORγ is associated with the development and progression of melanoma." (PMID 28323902, 2017). "In conclusion, our studies indicate that development and progression of melanoma is associated with decreased expression of RORα and RORγ, and that downregulation of RORs level is associated with unfavorable clinical prognosis." (PMID 27542227, 2016). "This study represents the first comprehensive analysis of RORα and RORγ in human melanocytic tumors in relation to several clinico-pathomorphological features associated with various stages of melanoma progression." (PMID 27542227, 2016). "Compared to healthy individuals, melanoma patients show significant RORA gene mutations." (PMID 39213172, 2024). "Another study examined the association of polymorphisms of steroid hormone receptors and melanoma prognosis, and found significant associations between cutaneous melanoma-specific survival and two SNPs on the clock gene RORA, whose putative protein encodes a ligand-activated transcription factor." (PMID 33549124, 2021). "Moreover, two variants of a clock gene, RORA, have been associated with melanoma patient’s prognosis." (PMID 33549124, 2021). "This study shows that human melanoma development and aggressiveness is associated with decreased expression of RORα and RORγ, suggesting that RORs could be important in melanoma progression and host responses against the tumor." (PMID 27542227, 2016). "Overall, we cannot conclude in favour of the hypothesis that variability of the circadian clock genes may affect melanoma susceptibility or prognosis, but we did find an interesting relationship between melanoma biology and RORA gene variants, which we believe is worth further investigation." (PMID 33549124, 2021). "Both nuclear and cytoplasmic RORα and RORγ decreased with progression lesions from nevi to primary melanomas to melanoma metastases." (PMID 38927967, 2024). "Primarily, RORα and RORγ expression is diminished in melanoma relative to benign nevi, with further decreases observed in advanced stages and metastatic lesions." (PMID 39518891, 2024). "The clock gene RORA is also significantly downregulated in melanoma and its low expression correlates with poor prognosis." (PMID 39213172, 2024). "An inverse correlation has been found between the levels of RORα and RORγ expression and melanoma progression and disease outcome." (PMID 35669434, 2022). "There was a reverse correlation between melanin content and expression of the VDR and CYP27B1 as well as of RORα and γ in human melanoma samples." (PMID 34692525, 2021). "RORA was found to be downregulated in melanoma compared to nevi, and the expression was directly correlated to overall and disease-free survival." (PMID 33549124, 2021).